L2HGDH (L-2-hydroxyglutarate dehydrogenase)
Description:
Catalyzes the oxidation of L-2-hydroxyglutarate to 2-oxoglutarate (alpha-ketoglutarate).
Synonyms: C14orf160; FLJ12618; L2HGA
Tractability: PROTAC: ubiquitination databases record sites on it; its protein half-life has been measured.
Gene: Protein-coding gene on chromosome 14 (50,237,563 to 50,312,229, reverse strand). Ensembl gene ENSG00000087299.
Subcellular location: Mitochondrion
Subcellular location (Human Protein Atlas): Mitochondria
Pathways (Reactome):
Metabolism: Interconversion of 2-oxoglutarate and 2-hydroxyglutarate
Gene Ontology:
Molecular function: (S)-2-hydroxyglutarate dehydrogenase activity; oxidoreductase activity, acting on CH-OH group of donors
Biological process: 2-oxoglutarate metabolic process; tricarboxylic acid cycle
Cellular component: membrane; mitochondrion; mitochondrial inner membrane
Genetic constraint (gnomAD): Loss-of-function variants: 28 observed, 44.02 expected, observed/expected ratio (o/e) 0.64, 90% interval 0.47 to 0.87. The upper end of that interval is the gene's LOEUF score, 0.87, which puts it in group 3 of 6, group 1 being the genes least tolerant of losing a copy. Missense variants: 524 observed, 538.36 expected, observed/expected ratio (o/e) 0.97, 90% interval 0.9 to 1.05. Synonymous variants: 188 observed, 192.82 expected, observed/expected ratio (o/e) 0.98, 90% interval 0.87 to 1.1.
Gene-disease validity (ClinGen):
ClinGen rates the evidence that L2HGDH causes each of these diseases.
mitochondrial disease (autosomal recessive): Definitive.
Homologues: Orthologues: chimpanzee L2HGDH (98% identical), macaque L2HGDH (97% identical), rabbit L2HGDH (90% identical), dog L2HGDH (89% identical), guinea pig L2HGDH (88% identical), mouse L2hgdh (83% identical), rat L2hgdh (81% identical), pig L2HGDH (76% identical), tropical clawed frog l2hgdh (68% identical), zebrafish l2hgdh (62% identical), Drosophila melanogaster L2HGDH (53% identical), Caenorhabditis elegans Y45G12B.3 (51% identical). Paralogues in human: DMGDH (19% identical), SARDH (19% identical), PDPR (19% identical), FOXRED1 (15% identical), AMT (11% identical), YPEL1 (5% identical), YPEL2 (5% identical), YPEL3 (5% identical), YPEL4 (4% identical), YPEL5 (3% identical).
Diseases named in the same sentence as L2HGDH in open-access papers:
L2HGDH is named in the same sentence as 45 diseases in open-access papers, as found by Europe PMC text mining. Sharing a sentence is not in itself a finding about the gene and the disease. The quoted sentences say what the papers report.
L-2-hydroxyglutaric aciduria (11 papers, 2015 to 2026). L-2-hydroxyglutaric aciduria is a primarily neurological form of 2-hydroxyglutaric aciduria characterized by psychomotor retardation, cerebellar ataxia and variable macrocephaly or epilepsy. "We have identified a homozygous L2HGDH variant, c.905C>T p.(Pro302Leu), in two siblings affected by L-2-hydroxyglutaric aciduria and demonstrated through functional assays that this variant disrupts the L2HGDH enzyme’s localization and activity." (PMID 40870031, 2025). "L-2-hydroxyglutaric aciduria (L-2-HGA) is a rare autosomal recessive neurometabolic disorder caused by pathogenic variants in L2HGDH, encoding the mitochondrial FAD-dependent L-2-hydroxyglutarate dehydrogenase." (PMID 40963932, 2025). "L-2-hydroxyglutaric aciduria is an autosomal recessive neurometabolic disorder characterized by the accumulation of L-2-hydroxyglutarate and caused by a deficiency in L-2-hydroxyglutarate dehydrogenase." (PMID 25763823, 2015). "L-2-hydroxyglutaric aciduria (L2HGA): In this disease, there is an accumulation of L-2-hydroxyglutaric acid due to a mitochondrial enzyme gene L2HGDH mutation." (PMID 35453911, 2022). "L-2-hydroxyglutaric aciduria (L2HGA) is a progressive neurometabolic disease of brain caused by mutations of in L-2-hydroxyglutarate dehydrogenase (L2HGDH) gene." (PMID 29458334, 2018). "L-2 hydroxyglutaric aciduria (L-2-HGA) is an autosomal recessive progressive, organic aciduria caused by a mutation in L-2 hydroxyglutarate dehydrogenase (L2HGDH) gene." (PMID 39262645, 2024). "The purpose of the present work was to progress in our understanding of the pathophysiology of L-2-hydroxyglutaric aciduria, due to a defect in L-2-hydroxyglutarate dehydrogenase, by creating and studying a mouse model of this disease." (PMID 25763823, 2015). "In addition, L2HGDH, encoding the FAD-dependent L-2-hydroxyglutarate dehydrogenase, is mutated in L-2-hydroxyglutaric aciduria." (PMID 40963932, 2025).
cerebellar ataxia (4 papers, 2020 to 2026). A neurological syndrome characterized by clumsy and uncoordinated movement of the limbs, trunk, and cranial muscles. "Patients with biallelic L2HGDH variants have exclusive neurological findings of psychomotor retardation, cerebellar ataxia, macrocephaly, and epilepsy." (PMID 33426505, 2020).
2-hydroxyglutaric aciduria (3 papers, 2014 to 2024). "L-2-HG can also accumulate by defects in the L-2-HG processing enzyme L-2-hydroxyglutarate dehydrogenase (L2HGDH) and is the cause of the disorder 2-hydroxyglutaric aciduria." (PMID 32709924, 2020).
brain tumors (3 papers, 2016 to 2026). "L-2HG dehydrogenase (L2HGDH) deficiency, a rare autosomal recessive inborn error of metabolism associated with systemic L-2HG elevation, causes progressive neurological disability and increased brain tumor risk of unclear mechanism." (PMID 41842973, 2026). "Interestingly, we found out that several components from the MSC possess biomarker properties that are relevant for the development and treatment of brain tumors, especially pyruvate and L2HGDH." (PMID 31208363, 2019).
epilepsy (3 papers, 2020 to 2026). A brain disorder characterized by episodes of abnormally increased neuronal discharge resulting in transient episodes of sensory or motor neurological dysfunction, or psychic dysfunction. "To date, no case has been reported of a patient with L2HGA caused by the c.905C>T variant in L2HGDH presenting with epilepsy, tetraspasticity, tetraataxia, dysarthria, and dysmorphism, but without cognitive impairment or gait disturbance." (PMID 42205672, 2026).
renal cell carcinoma (3 papers, 2018 to 2024). "L-2HG accumulates in brain tumors and also in kidney tumors (like renal cell carcinoma, RCC) as the consequence of a mutated L-2HGDH enzyme." (PMID 39201738, 2024). "In addition, L-2HG levels are elevated in the most common histology (clear cell) of renal cell carcinoma (RCC) owing to loss of expression of L2HGDH." (PMID 32928875, 2020). "Finally, our studies in the fly support a previous study of renal cell carcinomas, which revealed that aberrant L-2HG accumulation results from decreased L2HGDH activity." (PMID 30108060, 2018).
clear cell renal carcinoma (2 papers, 2020 to 2023). A malignant epithelial neoplasm of the kidney characterized by the presence of lipid-containing clear cells within a vascular network. "Increased L‐2HG has been reported in clear cell renal cell carcinoma due to loss or dysfunction of L‐2HG dehydrogenase (L2HGDH) to convert L‐2HG to α‐KG, which is largely associated with gene deletion on 14q, a region coding for L2HGDH." (PMID 37601838, 2023).
CNS-cancer (2 papers, 2019 to 2025). "Further, the gene L-2-hydroxyglutarate dehydrogenase (L2HGDH) (spearman = − 0.252, p < 0.005) has been identified in the MSC, showing that the expression level of this gene may be an indication of treatment outcome for these eight RTK inhibitors in CNS-cancer cell lines." (PMID 31208363, 2019).
Cognitive impairment (1 paper, 2026). Abnormal cognition is characterized by deficits in thinking, reasoning, or remembering. "This case broadens the phenotypic spectrum of L2HGA and demonstrates that the c.905C>T variant in the L2HGDH gene can manifest phenotypically with only mild symptoms and without cognitive deficits or gait abnormalities." (PMID 42205672, 2026).
colon cancer (1 paper, 2023). "L2HG concentrations averaged 54 nmol/g tissue in human colon cancer tissue and 217 nmol/g tissue in L2HGDH knockdown tumors." (PMID 36879117, 2023).
COVID-19 (1 paper, 2023). A disease caused by infection with severe acute respiratory syndrome coronavirus 2. "Mitochondrial proteins such as MRPL, L2HGDH, ATP, CYB, CYTB, CYP, NDUF and others, were increased in COVID-19 and ICU-ARDS plasma." (PMID 37031181, 2023). "Mitochondrial proteins such as ATP5A1, CYB561D1, several CYP accessions, L2HGDH, two MRP, MRPL37, NDUFS1 and others showed increased observation frequency across COVID-19 and ICU-ARDS versus NHP individually by the Chi Square test (χ2 ≥ 10, p ≤ 0.01) and as a group by one way ANOVA (p ≤ 0.003)." (PMID 37031181, 2023).
leukemia (1 paper, 2018). A malignant (clonal) hematologic disorder, involving hematopoietic stem cells and characterized by the presence of primitive or atypical myeloid or lymphoid cells in the bone marrow and the blood. "The following sections summarize the eight top-ranked genes in some of the major drug classes (FLT3, CASP8AP2, L2HGDH, MNT, BAZ2B, MZF1, BEX2, and SMARCA4) that are highly likely to have notable biological significance in leukemia." (PMID 29298978, 2018).
metastatic tumour (1 paper, 2022). "Previous research in a similarly sized cohort of patients with paired primary and matched metastatic tumour samples, identified somatic copy number losses at 9p21 (CDKN2A) and 14q (L2HGDH, HIF1A) as critical molecular alterations towards the development of metastatic disease in patients with ccRCC." (PMID 35231161, 2022).
renal carcinoma (1 paper, 2022). A carcinoma arising from the epithelium of the renal parenchyma or the renal pelvis. "Previously, a knockdown of L2HGDH was observed not only to cause an increase in L2HG levels, but in addition to cause alterations in the level of DNA hydroxymethylation and histone methylation in renal carcinomas and other cultured renal cells." (PMID 36133305, 2022).
renal tumor (1 paper, 2020). "Bioinformatic analysis of mRNA expression data from renal tumors demonstrates that L2HGDH is co-expressed with genes encoding TCA cycle enzymes as well as the gene encoding the transcription factor PGC-1α, which is known to regulate mitochondrial metabolism." (PMID 32928875, 2020). "Restoration of PGC-1α in renal tumor cells results in increased L2HGDH expression with a concomitant reduction in L-2HG levels." (PMID 32928875, 2020). "As further evidence, we identified several renal tumors with low L2HGDH expression/elevated L-2HG without L2HGDH copy loss." (PMID 32928875, 2020).
tumor (9 papers, 2010 to 2023). "Both increased L-2HG and L2HGDH knockdown led to diminished 5-hmC level, which is strongly associated with tumor aggressiveness and an unfavorable prognosis, and restoring the activity of TET2 leads to inhibition of ccRCC growth both in vitro and in vivo." (PMID 33842477, 2021). "Using this as a rationale to explainalternate methods of 2HG production, a recent study examined secondary GBMs and otherCNS tumours for inactivating mutations of D2HGDH or L2HGDH." (PMID 21317451, 2010). "Alternatively, if 2HG accumulation is critical, some tumours might acquire somatic D2HGDH or L2HGDH mutations." (PMID 21625441, 2011). "To investigate the function of L2HG in vivo, we evaluated the effect of L2HGDH knockdown on tumor growth using a mouse xenograft model." (PMID 36879117, 2023). "Together, these data suggest that L2HGDH has metabolic tumor suppressor activity and is an epigenetic regulator in kidney cancer." (PMID 26097881, 2015). "Lowering L-2HG levels in RCC through re-expression of L2HGDH mitigates tumor phenotypes and reverses epigenetic alterations known to be targeted by oncometabolites." (PMID 26097881, 2015). "Therefore, L2HGDH acts a tumor suppressor in ccRCC, and the accumulated L-2HG is thought to be an oncometabolite." (PMID 33842477, 2021). "The characterization of L2HGDH as a tumor suppressor was much more comprehensive than HIF1α." (PMID 33077781, 2020). "L2HGDH has been shown to suppress in vitro cell migration and in vivo tumor growth." (PMID 33077781, 2020). "Interestingly, L2HGDH (L-2-Hydroxyglutarate Dehydrogenase), a recently characterized epigenetic modulating ccRCC tumor-suppressor with a marked impact on survival, was found to be located only ~ 11.5Mbp from HIF1A on 14q (at 14q21.3)." (PMID 33077781, 2020). "It is possible that some of these genes are not functionally tumor suppressive, and that their association with survival is secondary to a strong correlation between their gene expression and that of L2HGDH (along with other co-deleted functionally tumor suppressive genes)." (PMID 33077781, 2020). "Furthermore, L2HGDH reconstitution in RCC cell lines suppressed in vitro tumor phenotypes." (PMID 26097881, 2015). "Hypoxia-induced L2HG production also contributed toward amino acid metabolism via the mTOR-ATF4 axis and L2HGDH knockdown in a mouse xenograft model increased L2HG levels and promoted CRC tumor growth." (PMID 36879117, 2023). "Previous studies have demonstrated that hypoxic conditions, such as those found in the tumor microenvironment, elevate L2HG levels by upregulating LDH/MDH or downregulating L2HGDH." (PMID 36879117, 2023). "Here, we found that ectopic L2HGDH expression reduced intracellular L2HG levels and inhibited CRC tumor growth in vivo." (PMID 36879117, 2023). "Lastly, even between L2HGDH and HIF1A loci, 14q was found to have several other yet-to-be-characterized potential ccRCC tumor-suppressors." (PMID 33077781, 2020). "Furthermore, L2HGDH overexpression reduced L2HG-mediated mTOR-ATF4 signaling under hypoxia, whereas L2HGDH knockdown promoted tumor growth and amino acid metabolism in vivo." (PMID 36879117, 2023). "Based on the results of preclinical studies, future randomized clinical trials should be designed to evaluate vitamin C activity in specific tumor molecular subtypes, such as those characterized by HIF-1α over-expression and TET2, L2HGDH, IDH1/2, or WT1 altered pathways." (PMID 33804775, 2021).
cancer (2 papers, 2023 to 2024). A tumor composed of atypical neoplastic, often pleomorphic cells that invade other tissues. "In RCC, decreased L2HGDH levels have been reported to lead to L2HG accumulation, contributing toward cancer malignancy." (PMID 36879117, 2023).
metabolic disease (2 papers, 2022). A congenital disorder (due to inherited enzyme abnormality) or acquired (due to failure of a metabolically important organ) disorder resulting from an abnormal metabolic process. "S-2-Hydroxyglutarate is present in urine of healthy individuals and is elevated in patients with an inborn metabolic disease that results from L2hgdh deficiency." (PMID 35799259, 2022). "No similar study on L2HGDH gene has been documented so far, meaning this is the first in silico study on all reported L2HGDH mutations, which can provide a better understanding of the topic for researchers and scientists in the field of genetics and metabolic disorders." (PMID 35456504, 2022).
cardiovascular diseases (1 paper, 2024). "On the other hand, L2HGDH deletion–induced l-2-HG accumulation has been reported to preserve cardiac function under hypoxia conditions in mice, suggesting that L2HGDH inhibition is a potential therapeutic strategy for cardiovascular diseases related to oxidative injury." (PMID 37995940, 2024).
L2HGDH also shares sentences with these, for which no sentence is quoted: glioblastoma (2 papers); allergies (1); astrocytoma (1); Azoospermia (1); bladder cancer (1); Canavan disease (1); central nervous system neoplasm (1); coronary atherosclerosis (1); Dystonia (1); essential hypertension (1); genetic diseases (1); glioma (1); Hypertension (1); Intellectual disability (1); kidney cancer (1); Leukoencephalopathy (1); Macrocephaly (1); malignant brain tumors (1); medulloblastoma (1); Organic aciduria (1); primitive neuroectodermal tumor (1); psychomotor developmental delay (1); rheumatoid arthritis (1); Tremor (1); type 2 diabetes (1); X-linked creatine transporter deficiency (1).